RN7SL101P (RNA, 7SL, cytoplasmic 101, pseudogene)
Gene: Miscellaneous RNA gene on chromosome 4 (28,711,198 to 28,711,476, forward strand). Ensembl gene ENSG00000243548.
Homologues: Orthologues: chimpanzee Metazoa_SRP (97% identical), macaque Metazoa_SRP (87% identical). Paralogues in human: RN7SL1 (76% identical), RN7SL2 (76% identical), RN7SL709P (74% identical), RN7SL201P (74% identical), RN7SL3 (74% identical), RN7SL45P (73% identical), RN7SL174P (72% identical), RN7SL18P (72% identical), RN7SL778P (72% identical), RN7SL481P (72% identical), RN7SL496P (72% identical), RN7SL126P (71% identical), and 700 more.